COX7A2P2 (cytochrome c oxidase subunit 7A2 pseudogene 2)
Synonyms: COX7AL2; formerly COX7A3; COX7AP2
Gene: Processed pseudogene on chromosome 4 (96,902,801 to 96,903,050, forward strand). Ensembl gene ENSG00000236764.
Subcellular location: Mitochondrion inner membrane
Diseases named in the same sentence as COX7A2P2 in open-access papers:
COX7A2P2 is named in the same sentence as 1 disease in open-access papers, as found by Europe PMC text mining. Sharing a sentence is not in itself a finding about the gene and the disease.
COX7A2P2 shares sentences with these, for which no sentence is quoted: prostate carcinoma (1 paper).